TNNT2 (troponin T2, cardiac type)
Diseases named in the same sentence as TNNT2 in open-access papers (continued):
Sharing a sentence is not in itself a finding about the gene and the disease.
hypertrophic cardiomyopathy (42 papers, 2012 to 2025). "In humans, mutations in TNNT2 are major causes of hypertrophic cardiomyopathy and dilated cardiomyopathy, which are diseases that affect the heart muscle, causing structural and functional cardiac abnormalities." (PMID 38194447, 2024). "The results revealed that various TNNT2 variants exhibit different pathogenic mechanisms, greatly expanding the knowledge of which and how TNNT2 variants cause hypertrophic cardiomyopathy (HCM) and DCM." (PMID 36895064, 2023). "Tnnt2 is also associated with hypertrophic cardiomyopathy, dilated cardiomyopathy, and restrictive cardiomyopathies." (PMID 38110334, 2023). "TNNT2 sporadic and hot spot mutations associated to Hypertrophic CardioMyopathy (HCM) and prevalence of arrhythmias and clinical phenotype." (PMID 35514357, 2022). "The Δ160E mutation in TNNT2, which encodes troponin T, is a rare pathogenic variant identified in patients with hypertrophic cardiomyopathy and is associated with poor prognosis." (PMID 35861968, 2022). "CELF4 is a known splicing regulator of cardiac troponin T (TNNT2), which plays an essential role in calcium signaling in cardiac muscle, and rare genetic variants in TNNT2 are associated with familial dilated and hypertrophic cardiomyopathy." (PMID 34575190, 2021). "Mutations in TNNT2 lead to dilated cardiomyopathy (enlarged heart effecting pumping) or familial hypertrophic cardiomyopathy (abnormal thickening of heart muscles leading to difficulty in pumping blood)." (PMID 34722422, 2021). "Second, we found TNNT2 under the linkage peak on chromosome 1 for QT, which harbors known mutations underlying hypertrophic cardiomyopathy and familial dilated cardiomyopathy." (PMID 27877193, 2016). "Note, loss of function mutations in the human TNNT2 gene is linked to hypertrophic cardiomyopathy." (PMID 39285385, 2024). "Interestingly, Tnnt2, which encodes the cardiac isoform of troponin T, has been shown to regulate hypertrophic cardiomyopathy." (PMID 36936413, 2023). "Isogenic iPSC-CMs recapitulate the prolonged calcium decay, relaxation impairment, and subsequent calcium-regulated signaling pathways caused by the TNNT2 Δ160E mutation and can serve as a human model for therapeutic development to prevent hypertrophic cardiomyopathy pathology." (PMID 35861968, 2022). "Structural disorders include hypertrophic cardiomyopathy (HCM), the most prevalent cause, accounting for 35% of confirmed cases in the U.S., characterized by mutations in genes like MYH7, MYBPC3, and TNNT2." (PMID 40724525, 2025). "Analysis of a more specific ontology, cardiac hypertrophy – NF-AT signaling, revealed similar genes as the general hypertrophic cardiomyopathy ontology such as Myh6, Myh7, Tnnt2, Tnni3, and Actc1." (PMID 24475304, 2014). "Further analysis, of the genes affected within the hypertrophic cardiomyopathy ontology, identified many structural genes including troponin I (Tnni3), troponin T (Tnnt2), troponin C (Tnnc1), α-actin C1 (Actc1) that are important for proper cardiac function." (PMID 24475304, 2014). "The present study comprised sarcomeric genotyping of the three most commonly involved sarcomeric genes: MYBPC3, MYH7, and TNNT2 in 192 unrelated Egyptian hypertrophic cardiomyopathy (HCM) index patients." (PMID 23233322, 2013). "Raffaele Coppini conducted a cohort study of patients with hypertrophic cardiomyopathy (HCM), the outcome indicated that, among patients with HCM, most patients have a mutation in TNNT2, and these patients are more likely to suffer from arrhythmias and HCM in the future." (PMID 34046076, 2021). "In human, mutation of TnnT2 is tightly associated with hypertrophic cardiomyopathy, dilated cardiomyopathy, and left ventricular noncompaction cardiomyopathy." (PMID 27938398, 2016).
hypertrophic cardiomyopathy (continued). "Our previous study on cardiac Troponin I3 (TNNI3) and Troponin T2 (TNNT2) in hypertrophic cardiomyopathy (HCM), and cardiac actin (ACTC), myosin binding protein C (MyBPC3), had revealed few variants, of which a 25 bp deletion was found to be associated with both HCM and DCM in India and south Asia." (PMID 24992688, 2014). "Furthermore, some of these genes, including TNNC1, TNNT2 and ACTC1, enriched the Hypertrophic cardiomyopathy (HCM) pathway." (PMID 34069910, 2021). "Next, our KEGG analysis showed that transcripts up-regulated in the mutant cardiomyocytes were related to hypertrophic cardiomyopathy (ACTC1, MYL2, MYL3), Ca2+-dynamics regulatory pathway (ATP2B4, CACNA1C, CAMK2B, PLN), as well as cardiac-muscle contraction transcripts (ACTC1, MYH7, TNNI3, TNNT2)." (PMID 35784482, 2022).
dilated cardiomyopathy (38 papers, 2009 to 2026). Cardiomyopathy which is characterized by dilation and contractile dysfunction of the left and right ventricles. "A significant association between SNPs rs3729547 and rs3729843 within TNNT2 and dilated cardiomyopathy (DCM) has been found in the Chinese Han population." (PMID 40430031, 2025). "Hypertrophic and dilated cardiomyopathy causing mutations have been detected mostly in genes of sarcomere proteins such as Mybpc2, Myh7, Tnnt2, Tnnc1, Tnni3, Tpm1, Ttn, Actc1, Myl2, and Myl3." (PMID 38981849, 2024). "In conclusion, our findings uncovered the importance of XIN in TNNT2 mutation induced dilated cardiomyopathy." (PMID 34222259, 2021). "TNNT2 mutation is associated with a range of cardiac diseases, including dilated cardiomyopathy (DCM)." (PMID 34222259, 2021). "Detailed mechanisms for dilated cardiomyopathy caused by TNNT2 gene mutation remain largely unknown." (PMID 34222259, 2021). "Patients and methods: Three families with dilated cardiomyopathy (DCM) and pathogenic variants in the troponin T2, Cardiac Type (TNNT2) gene were included." (PMID 37108997, 2023). "Variants of uncertain significance (VUS) were found in 17 cases (eight resuscitated and nine dead) in genes associated with HCM or dilated cardiomyopathy (DCM), such as TTN, TNNT2, MYH6, DSP, ACTN2, CALR3, and MYH7." (PMID 36588553, 2022). "In the present study, we were able to successfully rescue cardiac remodeling in a TNNT2-ΔK210 mouse model of dilated cardiomyopathy by overexpressing XIN." (PMID 34222259, 2021). "Mutations in TNNT2 have been strongly implicated in the development of HCM and dilated cardiomyopathy." (PMID 33304277, 2020). "Although patients with CCM had rare variants in several established dilated cardiomyopathy (DCM) genes (BAG3, LMNA, MYH7, TCAP, TNNT2, and TTN), only variants in TTN, which encodes titin, were significantly increased." (PMID 30987448, 2019). "Mutations in the cardiac isoform of TnT (TNNT2) are associated with familial HCM, dilated cardiomyopathy, or arthrogryposis." (PMID 28866639, 2017). "TNNT2 mutations have additionally been implicated in other myocardial diseases including dilated cardiomyopathy, restrictive cardiomyopathy, and left ventricular noncompaction." (PMID 37180798, 2023). "Interestingly, in both the HIV vs. HIV+PSU and WT+PSU vs. HIV+PSU comparisons, Tnnc1, Tnnt2, and Actc1 were found to be majorly involved in the calcium signaling and dilated cardiomyopathy (DCM) signaling pathways." (PMID 37766354, 2023). "The introduction of the dilated cardiomyopathy (DCM)-causing TNNT2 mutation ΔK210 in reconstituted thin filaments led to decreased Ca2+-sensitivity when using WT and ΔK210 cTnT in a 50:50 ratio, whereas it resulted in increased Ca2+-sensitivity when using 100% ΔK210." (PMID 33148509, 2021). "Moreover, in dilated cardiomyopathy pathway core enrichment, integrins (Itga1, Itga10, Itga8 and Itgb6) and cellular components of troponin system (Tnni3, Tnnc1 and Tnnt2) appeared modulated, besides Cox and Myh genes." (PMID 24252798, 2013). "Dilated cardiomyopathy (DCM) pathway, including Lama2, Tnnt2, Actg1, Atp2a2, Gnas, Tpm3, Itga6, Tpm1, and Pln, was enriched in the KEGG pathway." (PMID 37858115, 2023).
Arrhythmia (30 papers, 2010 to 2025). Any cardiac rhythm other than the normal sinus rhythm. "Previous cases have been reported in which TNNT2 mutations are associated with only minor or subclinical left ventricular hypertrophy but carry a high risk of arrhythmia." (PMID 37180798, 2023). "CMs with mutations in Tnnt2 (R92Q) demonstrated spontaneous calcium waves and transients, burst contractions or extreme relaxation prolongations were found in Mybpc3 KI CMs,82 and CMs showed arrhythmia after isoproterenol administration." (PMID 40306862, 2025). "Due to the fact that the loss of TNNT2 may lead to heart rhythm disorder and impaired cardiovascular function, so the downregulation of TNNT2 may symbolize the decline of cardiac function in DN patients." (PMID 35637650, 2022). "A study conducted using zebrafish embryos suggested that zebrafish embryos exposed to procymidone are more likely to alter transcription levels of TNNT2 and resulted in arrhythmia as well as increased heart rate finally." (PMID 34046076, 2021). "Furthermore, downstream genes (MYH6, MYH7, TNNT2, NKX2-5, and CCND1) regulated by SFRP4 partake in ICM-related diseases like HF and arrhythmias." (PMID 40066352, 2025).
cardiac hypertrophy (29 papers, 2009 to 2025). "Unlike the general anatomical abnormalities normally found in HCM patients, hearts from patients harboring cardiac troponin T (TNNT2) variants typically show significantly less ventricular hypertrophy compared to other HCM-associated variants." (PMID 34977031, 2021). "In addition, we analysed the cardiac expression of different genes that are associated with cardiac hypertrophy including cardiac troponin (Tnnt2), Fgf23 and natriuretic peptide type B (Nppb)." (PMID 39637045, 2024). "In the present study, we assessed the mRNA expression levels of ANP, BNP, and TNNT2 in cardiomyocytes to investigate the combined effects of SE and harmine in the treatment of cardiac hypertrophy." (PMID 39351650, 2024). "Atrial Natriuretic Peptide (ANP), B‐type Natriuretic Peptide (BNP), and Cardiac Troponin T (TNNT2) are biomarkers that are known to increase in pathological cardiac hypertrophy." (PMID 39351650, 2024). "A few case reports describing the clinical phenotype of families with severe TNNT2-associated HCM highlighted a high incidence of ventricular and atrial arrhythmias, including AF, despite relatively mild ventricular hypertrophy." (PMID 35514357, 2022). "Initial clinical phenotype descriptions of TNNT2 mutations were from families with severe HCM (cTnT-HCM), characterized by mild hypertrophy and high incidence of sudden cardiac death (SCD)." (PMID 35514357, 2022). "Genetic variants of MYH6, TNNT2 and TPM1, have been found to be associated with hypoplastic left heart, cardiac hypertrophy and DCM, respectively." (PMID 32423033, 2020). "To elaborate on the DNA methylation array results, we selected several DMRs at different gene loci related to cardiac hypertrophy including Mef2c, Tnnt2, Myh6, Myh7, and Gata4 and body weight Ins2 for bisulfite sequencing." (PMID 24475304, 2014). "Among thousands of different variants found in HCM patients, variants of TNNT2 (cardiac troponin T—TNNT2) are linked to increased risk of ventricular arrhythmogenesis and sudden death despite causing little to no cardiac hypertrophy." (PMID 34977031, 2021). "Gene expression of cardiac hypertrophy related genes such as MYH6, TNNT2, NPPA, and NPPB was modestly induced in ISO-treated WT hESC-CMs, but was found to be markedly elevated in MLP KO hESC-CMs." (PMID 31406109, 2019).
left ventricular hypertrophy (19 papers, 2012 to 2025). Enlargement of the LEFT VENTRICLE of the heart. "Mutations of TNNT2 are associated with high risk of sudden cardiac death despite mild left ventricular hypertrophy." (PMID 39125703, 2024). "For example, TNNT2 mutations in patients are generally associated with a high incidence of sudden death despite only mild left ventricular hypertrophy." (PMID 23700405, 2013).
Ventricular arrhythmia (12 papers, 2016 to 2026). "In 24 mice models ventricular arrhythmias were reported, most frequently in models with sarcomere mutations: Tnnt2 (n = 10 [41.7%]), Myh6 (n = 4 [16.7%]), and Mybpc3 (n = 3 [12.5%])." (PMID 40306862, 2025). "Indeed, there was a direct correlation between the degree of calcium sensitization and the risk for ventricular arrhythmias in TNNT2 mutant mice." (PMID 36768995, 2023). "When excluding the more prevalent TNNT2 and MYBPC3 variants in HCM G+P− individuals, the occurrence of ventricular arrhythmias (OR 1.72 [95% CI 0.44;4.89], P=0.306) and atrial arrhythmias (OR 1.43 [95% CI 0.84;2.32], P=0.156) was comparable to G−P− controls." (PMID 36264615, 2022). "A recent meta‐analysis reported that myosin the MYH7 mutation group showed the highest rate of ventricular arrhythmia compared with the MYBPC3, TNNT2, and TNNI3 mutation group." (PMID 32815161, 2020). "Ventricular arrhythmias were induced in 17 studies and occurred spontaneously in 7 studies, of which 3 studies reported on sarcomeric mutations (Tnnt2 [F110I, I79N, R92Q] and Mybpc3 [KI]) and 4 on nonsarcomeric mutations." (PMID 40306862, 2025).
restrictive cardiomyopathy (5 papers, 2017 to 2023). A type of heart disorder referring to the inability of the ventricles to fill with blood because the myocardium (heart muscle) stiffens and looses its flexibility. "Restrictive cardiomyopathy is a rare cardiac disease, for which several genes including TNNT2, MYPN, FLNC and TNNI3 have been associated with its familial form." (PMID 30953456, 2019).
colorectal cancer (4 papers, 2022 to 2025). A primary or metastatic malignant neoplasm that affects the colon or rectum. "Our study showed that there was a significant difference in the expression of TNNT2 between colorectal cancer tissue and paraneoplastic tissue, and TNNT2 was highly expressed in colorectal cancer tissue and expressed at low levels in paraneoplastic tissues." (PMID 37481519, 2023). "Our results and the effect of TNNT2 on metastasis and the mechanism of TNNT2 in colorectal cancer are also discussed herein." (PMID 37481519, 2023). "TNNT2 is expressed at a low level in normal colon tissues but is significantly upregulated in colorectal cancer tissues." (PMID 37481519, 2023). "CCK-8, colony formation, Transwell and other experiments were used to clarify the role of TNNT2 in the proliferation, migration and invasion of colorectal cancer cells." (PMID 37481519, 2023). "Many studies have shown that TNNT2 is abnormally highly expressed in colorectal cancer and lung cancer, and is related to tumor grading and differentiation." (PMID 37481519, 2023). "The results suggest that the expression of TNNT2 in colorectal cancer tissues is higher than that in paraneoplastic tissue." (PMID 37481519, 2023). "Notably, TNNT2 maintained its ability to promote the proliferate colorectal cancer cells after a long time." (PMID 37481519, 2023). "TNNT2 can promote the proliferation, invasion and metastasis of colorectal cancer cells." (PMID 37481519, 2023). "TNNT2 knockdown can inhibit the clonogenic ability of colorectal cancer cells." (PMID 37481519, 2023). "However, the mechanism of TNNT2 in colorectal cancer is still unclear." (PMID 37481519, 2023). "Furthermore, our studies have shown that TNNT2 can promote the growth, colony formation and migration of colorectal cancer cells, inhibit cell apoptosis and aging, and play a potential role in promoting colorectal cancer." (PMID 37481519, 2023). "This study reveals that TNNT2 can promote the invasion and metastasis of colorectal cancer through EGFR/HER2/EMT signal axis, and reveals the potential of TNNT2 as a therapeutic target for colorectal cancer." (PMID 37481519, 2023). "TNNT2 can upregulate EGFR and HER2-related proteins in colorectal cancer cells and promote the occurrence of EMT." (PMID 37481519, 2023).
Duchenne muscular dystrophy (4 papers, 2012 to 2025). Duchenne muscular dystrophy (DMD) is a neuromuscular disease characterized by rapidly progressive muscle weakness and wasting due to degeneration of skeletal, smooth and cardiac muscle. "It has been shown before by qPCR that many “DM1-specific” splice events are shared between DM1 and Duchenne muscular dystrophy (DMD) including, among others, MBNL1, ATP2A1, TTN, TNNT2 and MEF2A/C." (PMID 40149583, 2025).
familial dilated cardiomyopathy (4 papers, 2016 to 2022). A a genetic form of heart disease that occurs when heart (cardiac) muscle becomes thin and weakened in at least one chamber of the heart, causing the open area of the chamber to become enlarged (dilated). "Deletion of lysine 210 (ΔK210) in TNNT2 gene has been found to cause familial dilated cardiomyopathy (DCM), which is characterized by dilated ventricular chamber and reduced systolic function leading to progressive heart failure with high mortality." (PMID 34222259, 2021). "Similarly, iPSC lines have been generated from a family with familial dilated cardiomyopathy (DCM), caused by a mutation of the gene encoding cardiac troponin T (TNNT2)." (PMID 30053890, 2018).
ischemic cardiomyopathy (3 papers, 2023 to 2025). Ischemic cardiomyopathy is a cardiomyopathy in which a weakness in the muscle of the heart due to inadequate oxygen delivery to the myocardium with coronary artery disease being the most common cause. "Moreover, from the RNA‐seq data of human dilated and ischemic cardiomyopathy, the expression of Tnnt2 and Ttn was significantly negatively correlated with Actr5 expression (r = −0.3369, P = 0.0065 between Tnnt2 and Actr5; r = −0.3847, P = 0.0017 between Ttn and Actr5)." (PMID 36610028, 2023).
lung carcinoma (3 papers, 2020 to 2025). "Our data suggest the aberrant expression of TNNT2 in lung cancer and its prevalence increases with pathological severity." (PMID 35479276, 2022). "Lung cancer tissues obtained from four patients (2, squamous cell carcinoma, and 2, adenocarcinoma) demonstrated the expression of TNNT2 mRNA." (PMID 35479276, 2022). "We confirmed that gene expression of TNNT2 was detected in two major histologic types of lung cancer tissues." (PMID 35479276, 2022). "Biological function of TNNT2 in lung cancer needs to be determined in the future study." (PMID 35479276, 2022). "This study advances our understanding that an aberrant expression of TNNT2 in lung cancer cells, irrespective of histologic type, and in association with pathological severity." (PMID 35479276, 2022). "This study provides new insights into the TNNT2 expression in lung cancer tissues." (PMID 35479276, 2022). "Immunoreactivity for TNNT2 protein was present in the cytoplasm and nucleus of lung cancer cells." (PMID 35479276, 2022). "In addition, we examined whether TNNT2 gene is detected in lung cancer tissues of four patients using reverse transcription-polymerase chain reaction." (PMID 35479276, 2022). "This study reports that TNNT2 is present in lung cancer, irrespective of histologic types, and its prevalence increases with pathological severity." (PMID 35479276, 2022). "Third, only 37% of population exhibited the positive TNNT2 staining, and we could not determine the prognostic value in lung cancer specimens with many other confounding variables." (PMID 35479276, 2022).
myotonic dystrophy type 1 (3 papers, 2016 to 2024). Steinert disease, also known as myotonic dystrophy type 1, is a muscle disease characterized by myotonia and by multiorgan damage that combines various degrees of muscle weakness, arrhythmia and/or cardiac conduction disorders, cataract, endocrine damage, sleep disorders and baldness. "Missplicing of the TNNT2 gene has been observed in skeletal muscle in myotonic dystrophy type 1 (DM1)." (PMID 39390091, 2024).
rheumatoid arthritis (3 papers, 2018 to 2025). A chronic, systemic autoimmune disorder characterized by inflammation in the synovial membranes and articular surfaces. "Fasting responsive genes were also regulated by variants associated to Crohn’s disease (PTGER4), Rheumatoid arthritis (PHLDB1), Lung Function (ADAM19) and with cardiac troponin (TNNT2)." (PMID 30193568, 2018).